SLC35D3 (solute carrier family 35 member D3)
Description:
Probable UDP-glucose transmembrane transporter involved in UDP-glucose transport from the cytosol to the lumen of synaptic vesicles. It is involved in platelet dense granules maturation (By similarity). Alternatively, could function as a molecular adapter enhancing the formation of the PI3KC3-C1/AIC/autophagy initiation complex to promote autophagy in dopaminergic neurons. Could also regulate the plasma membrane localization of the D(1A) dopamine receptor/DRD1 and dopamine signaling.
Synonyms: FRCL1
Tractability: Antibody: UniProt predicts a signal peptide or a membrane-spanning region.
Gene: Protein-coding gene on chromosome 6 (136,922,301 to 136,925,660, forward strand). Ensembl gene ENSG00000182747.
Subcellular location: Cytoplasmic vesicle, secretory vesicle, synaptic vesicle membrane; Early endosome membrane; Endoplasmic reticulum membrane
Subcellular location (Human Protein Atlas): Centriolar satellite
Gene Ontology:
Molecular function: protein binding; UDP-glucose transmembrane transporter activity; protein-macromolecule adaptor activity
Biological process: UDP-glucose transmembrane transport; platelet dense granule organization; positive regulation of autophagy
Cellular component: synaptic vesicle membrane; early endosome membrane; endoplasmic reticulum; endoplasmic reticulum membrane; early endosome
Genetic constraint (gnomAD): Loss-of-function variants: 23 observed, 21.06 expected, observed/expected ratio (o/e) 1.09, 90% interval 0.79 to 1.54. The synonymous counts are far from expectation, so gnomAD's model fits this gene poorly and the ratio says little. Missense variants: 556 observed, 528.31 expected, observed/expected ratio (o/e) 1.05, 90% interval 0.98 to 1.13. Synonymous variants: 313 observed, 242.45 expected, observed/expected ratio (o/e) 1.29, 90% interval 1.18 to 1.42.
Homologues: Orthologues: chimpanzee SLC35D3 (99% identical), macaque SLC35D3 (98% identical), pig SLC35D3 (94% identical), rat Slc35d3 (93% identical), guinea pig SLC35D3 (93% identical), dog SLC35D3 (92% identical), mouse Slc35d3 (91% identical), rabbit SLC35D3 (88% identical), tropical clawed frog pex7 (69% identical), zebrafish SLC35D3 (62% identical). Paralogues in human: SLC35D1 (18% identical), SLC35D2 (16% identical), SLC35E2B (15% identical), SLC35E4 (15% identical), SLC35E1 (14% identical), SLC35H1 (13% identical), SLC35E3 (13% identical), SLC35C1 (12% identical), SLC35D4 (8% identical).
Diseases named in the same sentence as SLC35D3 in open-access papers:
SLC35D3 is named in the same sentence as 12 diseases in open-access papers, as found by Europe PMC text mining. Sharing a sentence is not in itself a finding about the gene and the disease. The quoted sentences say what the papers report.
colon cancer (4 papers, 2021 to 2025). "Ceacam5, Klk6, Slc35d3, Postn, and Muc2 mRNA analysis improves the detection of tumor cells in the lymph nodes of colon cancer patients." (PMID 37996411, 2023). "mRNA analysis of CEACAM5, KLK6, and SLC35D3 improves the detection of tumor cells in lymph nodes from patients surgically treated for colon cancer, and, together with POSTN and MUC2, it further allows characterization of the tumor cells with respect to aggressiveness and the tumor cell environment." (PMID 34192710, 2021).
metabolic syndrome (3 papers, 2014 to 2023). A cluster of metabolic risk factors for CARDIOVASCULAR DISEASES and TYPE 2 DIABETES MELLITUS. "It has also been reported that mutation of Slc35d3 causes metabolic syndrome by impairing dopamine signaling in striatal D1 neurons in mice." (PMID 37996411, 2023). "Here we characterized the features of obesity and metabolic syndrome with reduced physical activity levels in a previously identified ros mouse mutant, carrying a homozygous Slc35d3 mutation." (PMID 24550737, 2014). "In addition, we identified two mutations of SLC35D3 in patients with metabolic syndrome which are subcellularly mislocalized." (PMID 24550737, 2014). "In addition, SLC35D3 is a candidate gene for obesity-related metabolic syndrome that is involved in metabolic control of the central nervous system by regulating dopamine signaling." (PMID 37996411, 2023). "Mutation of SLC35D3 leads to DG deficiency in platelets or storage pool deficiency (SPD) and metabolic syndrome (MetS) in brain." (PMID 30104399, 2018).
Obesity (3 papers, 2014 to 2023). Accumulation of substantial excess body fat. "We proposed that the decreased expression level of Notch1 was the primary molecular mechanism underlying the physiological function of Slc35d3 in regulating obesity in mice." (PMID 37996411, 2023). "Adipocyte-specific Slc35d3 knock-in promotes browning of white adipose tissues and ameliorates obesity, while Slc35d3 knockout can cause the opposite phenotypes." (PMID 37996411, 2023). "Considering that obesity affects 10∼25% of the European population and nearly one third of the US population, a mutational screen of SLC35D3 in the obese population would be cost-effective as a precursor to potential D1R agonist treatment." (PMID 24550737, 2014). "Our study reveals a regulatory function of SLC35D3 in obesity, and low SLC35D3 expression in adipose tissues might be a potential therapeutic target for obesity and associated metabolic disorders." (PMID 37996411, 2023). "Genome-wide linkage analyses have revealed that an STS marker D6S1009 (about 55 kb from the SLC35D3 gene) is linked to obesity or BMI in the Framingham Heart Study, but its genetic entity is unknown." (PMID 24550737, 2014). "SLC35D3 deficiency caused obesity primarily via effects on physical activity levels, supporting that genetic factors could be a component of low physical activity." (PMID 24550737, 2014). "In addition, the two patients with SLC35D3 mutations were diagnosed with adult central obesity, which also suggests a late-onset obesity phenotype in humans." (PMID 24550737, 2014). "SLC35D3 is expressed primarily in striatal neurons that project to the substantia nigra and the globus pallidus externa in the brain, and mice with a recessive mutation in the SLC35D3 gene have decreased motor activity, impaired energy expenditure, and develop obesity." (PMID 34269178, 2021). "Taken together, these data indicated that Slc35d3 knock-in protected mice from obesity and significantly improved obesity-related glucose intolerance and chronic inflammation, which was more marked in HFD-fed mice." (PMID 37996411, 2023). "Here, we demonstrated the role of SLC35D3 in regulating obesity and related metabolic disturbances by studying adipocyte-specific Slc35d3 knockout and knock-in mice." (PMID 37996411, 2023). "As expected, knockdown of Notch1 resulted in resistance to obesity as well as improved metabolism, which was more pronounced in Slc35d3 knockout mice." (PMID 37996411, 2023). "In conclusion, we identify that SLC35D3 is involved in obesity by interacting with the NOTCH1 extracellular domain and promoting the accumulation of NOTCH1 in the ER, which can lead to the inhibition of NOTCH1 signaling." (PMID 37996411, 2023). "In this study, we found that Slc35d3 expression was lower in the adipose tissue of obese mice and revealed the molecular mechanism by which Slc35d3 was involved in obesity and related fat metabolism." (PMID 37996411, 2023). "Taken together, these data indicated that adipose-specific Slc35d3 knockout induced obesity and hepatic lipid accumulation and significantly increased obesity-related glucose metabolic disorders and chronic inflammation." (PMID 37996411, 2023). "To elucidate the correlation between SLC35D3 and obesity, we examined Slc35d3 expression in adipose tissues from obese mice, including leptin deletion-induced obese (ob/ob) mice and diet-induced obesity (DIO) mice." (PMID 37996411, 2023). "While adipocyte-specific Slc35d3 knockin is protected against diet-induced obesity, adipocyte-specific Slc35d3 knockout inhibits white adipose tissue browning and causes decreased energy expenditure and impaired insulin sensitivity in mice." (PMID 37996411, 2023). "In SAKI mice, Notch1 signaling was suppressed by overexpressed Slc35d3, which was correlated with the protective efficacy against obesity." (PMID 37996411, 2023).
Obesity (continued). "To understand the specific role of adipocyte SLC35D3 in regulating obesity and adipose inflammation, we generated adipocyte-specific Slc35d3 knockout mice using the adiponectin Cre-lox system." (PMID 37996411, 2023). "Our results suggest that SLC35D3 is a candidate gene for obesity-related MetS, which is involved in metabolic control in the central nervous system by regulating dopamine signaling." (PMID 24550737, 2014). "While Slc35d3 knockout in mice can lead to increased susceptibility to obesity and impaired glucose tolerance, Slc35d3 knock-in can promote WAT browning and protect against obesity." (PMID 37996411, 2023). "Overall, in this study, we reveal that SLC35D3 is involved in obesity via NOTCH1 signaling, and low adipose SLC35D3 expression in obesity might be a therapeutic target for obesity and associated metabolic disorders." (PMID 37996411, 2023). "Here, we explored the effect of SLC35D3 in adipose tissue on obesity." (PMID 37996411, 2023). "All of these findings suggest an interesting function of SLC35D3 in obesity, and low SLC35D3 expression in adipose tissues in obesity might be a potential therapeutic target." (PMID 37996411, 2023). "In addition, knockdown of Notch1 shows considerable improvement in obesity and glucose and lipid metabolism, which is more pronounced in Slc35d3 knockout mice." (PMID 37996411, 2023). "We propose that the SLC35D3 gene is likely a novel candidate gene for MetS and obesity." (PMID 24550737, 2014). "Therefore, low SLC35D3 expression in adipose tissues might be a potential therapeutic target of obesity, and NOTCH1 inhibition could lead to greater gains." (PMID 37996411, 2023). "In addition, knockdown of Notch1 in mouse inguinal white adipose tissue mediated by orthotopic injection of AAV8-adiponectin-shNotch1 shows considerable improvement in obesity and glucolipid metabolism, which is more pronounced in adipocyte-specific Slc35d3 knockout mice than in knockin mice." (PMID 37996411, 2023). "In this study, we show that SLC35D3 regulates white adipose tissue browning and obesity via NOTCH1 signaling." (PMID 37996411, 2023). "Here, the authors show that SLC35D3 promotes white adipose tissue browning through the NOTCH1 signalling pathway and SLC35D3 may be a potential therapeutic target for obesity and related complications." (PMID 37996411, 2023). "To further assess the roles of adipocyte SLC35D3 in the regulation of obesity and adipose inflammation, in “reverse” experiments, we generated adipose-specific Slc35d3-knock-in (SAKI) mice by crossbreeding Slc35d3-WT mice carrying the LSL-Slc35d3 transgene locus with adiponectin-derived Cre mice." (PMID 37996411, 2023).
colorectal cancer (1 paper, 2024). A primary or metastatic malignant neoplasm that affects the colon or rectum. "SLC35D3 is highly expressed in colorectal cancer (CRC) tissue." (PMID 39764438, 2024).
tumor (3 papers, 2020 to 2023). "SLC35D3 was expressed in the epithelium derived tumor cells and POSTN in fibroblasts." (PMID 32049988, 2020). "Moreover, while KLK6 and SLC35D3 were CC-tumor specific in the sense that only CC tumor tissue expressed the biomarkers compared to normal colon tissue or normal colon epithelial cells, CEACAM5 and MUC2 were expressed at approximately the same levels in normal and cancerous colon tissues." (PMID 32049988, 2020). "We investigated the impact of LN tissue volume examined for detection of tumor cells using CEACAM5 mRNA levels as a proxy for tumor cell amounts, and KLK6 and SLC35D3 mRNAs as proxies for tumor cell aggressiveness." (PMID 34192710, 2021).
cancer (2 papers, 2020 to 2021). A tumor composed of atypical neoplastic, often pleomorphic cells that invade other tissues. "Immunohistochemical staining was performed for AXIN2, MYBL2, TGFBI, and SLC35D3, which represented that the part of cancer was deeper than that of normal." (PMID 35174154, 2021). "Comparison between patients categorized according to biomarker expression, using formula A, i.e. [KLK6/CEACAM5 + SLC35D3/CEACAM5 + POSTN/18S rRNA -MUC2/CEACAM5], with regard to risk for recurrence of disease and cancer death and observed recurrence 3 and 5 years after curative surgery." (PMID 32049988, 2020).
cardiovascular diseases (1 paper, 2020). "Our results uncover a previously unknown role of SLC35D3 in porcine adipogenesis, and suggest a fruitful area of research for improving the quality of porcine meat quality as well as its potential role in human cardiovascular diseases." (PMID 32087688, 2020).
SLC35D3 also shares sentences with these, for which no sentence is quoted: central obesity (1 paper); Glucose intolerance (1); glucose metabolic disorders (1); Impaired glucose tolerance (1); metabolic disorders (1).